IL1B (interleukin 1 beta)
Diseases named in the same sentence as IL1B in open-access papers (continued):
Sharing a sentence is not in itself a finding about the gene and the disease.
intervertebral disc degeneration (continued). "Furthermore, the recruited macrophages led to an increase in local IL-1β within the intervertebral disc, ultimately exacerbating the process of intervertebral disc degeneration." (PMID 39286222, 2024). "TNF-α and IL-1β are the important inflammatory factors for intervertebral disc degeneration, which can induce intervertebral disc degeneration by reducing the anabolism of extracellular matrix proteins (Chen;Hodges;James and Diwan, 2021; Kim;Hong;Lee;Jeon and Ha, 2021)." (PMID 35837544, 2022). "During intervertebral disc degeneration, inflammatory factors such as IL-1β and TNF-α stimulate the nucleus pulposus cells to activate IκB kinase, thereby degrading IκB protein after ubiquitination and phosphorylation and exposing the NF-κB dimers, particularly dimer p65–p50." (PMID 28512264, 2017). "Thus, our improved in vitro intervertebral disc degeneration model established with IL‐1β and TNF‐α intervention could be used in the further research for intervertebral disc degeneration." (PMID 32583517, 2020). "Given the recognized importance of IL-1β as a key mediator in the process of intervertebral disc degeneration (IVDD), the expression of IL-1β was subsequently evaluated in four Gene Expression Omnibus (GEO) datasets." (PMID 39704340, 2025). "Intervertebral disc degeneration (IVDD) is a common imaging change, and it is characterized by increased production of inflammatory cytokines such as IL-1β and elevated degradation of extracellular matrix (ECM)." (PMID 41163024, 2025). "In order to validate the potential transcription factor regulatory network, we conducted an analysis of the expression levels of IL-1β, ZEB2, TNFAIP6, and COL6A2 in intervertebral disc degeneration (IVDD) patients." (PMID 39704340, 2025). "The study aimed to investigate the effect of ginsenoside Rg1 on intervertebral disc degeneration (IVDD) in rats and IL-1β-induced nucleus pulposus (NP) cells, and explore its underlying mechanism." (PMID 38485818, 2024). "IL-1β and TNF-α are mainly produced and secreted by immune cells, the expression of which is positively correlated with age and degree of intervertebral disk degeneration, and consistent with our study results." (PMID 37679790, 2023). "SDC4 has an important effect on intervertebral disc degeneration induced by inflammatory factors, such as TNF-α and IL-1β." (PMID 36506585, 2022). "As a therapeutic approach for intervertebral disc degeneration, ES in various ranges (5, 10, 20, 50, and 100 μA) was conducted to inspect its effect through LCCS that was developed for human NP cells induced by IL-1β inflammation." (PMID 34832700, 2021). "Previous studies have shown that intervertebral disc degeneration is a complex process of multi-factor interaction, in which a variety of cytokines are involved in the pathological progression of IVDD, e.g. IL-1β, TNF-α, IL-6." (PMID 34483910, 2021). "Furthermore, it was reported that UTI effectively inhibited the increased expression of MMP-2, MMP-3, NOS in degenerated NP cells induced by IL-1β in vitro which suggests that UTI may potentially be useful for clinical therapy of intervertebral disc degeneration." (PMID 27638499, 2016).
amyloid (46 papers, 2006 to 2025). "In amyloidosis, bacterial components such as LPS and metabolites, formed by bacteria such as SCFAs, and TMAO have been associated with amyloid deposits and pro-inflammatory cytokines (e.g., interleukin-1β (IL-1β) and IL-6)." (PMID 39857728, 2025). "It was shown that the modeling of amyloidosis caused an increase in the expression of mRNA of the proinflammatory cytokine Il-1β, which indicated the activation of astrocytes." (PMID 36555569, 2022). "Regarding the mechanism of inflammation in amyloidosis, pro-inflammatory cytokines such as IL-1β, IL-6, and TNF-α are associated with the formation of amyloid plaques, and these cytokines are proposed to trigger inflammatory responses and promote tissue damage." (PMID 40571902, 2025). "Interestingly, amyloid-induced reduction in β-cell phospho-PKB levels was associated with elevated IL-1β levels in human islets." (PMID 29474443, 2018). "In addition, both IL-1β and IL-6 are also known as key mediators in chronic inflammation and are associated with long-term hemodialysis complications such as erythropoietin hyporesponsiveness, cardiovascular morbidities and amyloidosis-related bone disease." (PMID 29069222, 2017). "Recently, it was reported that disruption of the NLRP3 inflammasome, which reduces conversion of pro-IL-1β to mature IL-1β, among other actions, ameliorates the phenotype of both mouse models of amyloidosis and models of tauopathy." (PMID 41191631, 2025). "Aβ+ Tregs specifically induced a reduction of IL-1β in AD mice which were received Tregs at later stages (9 months old) under amyloid enriched environment." (PMID 36451854, 2022). "Increased neuronal IL-1β expression is present in a transgenic rat model of amyloidosis before amyloid plaque deposition." (PMID 34218796, 2021). "Taken together, biological strategies that block specific immune mediators such us TNF-α or IL-1β are effective in suppressing the disease activity, preventing reactive amyloidosis, and halting the progression of organ damage." (PMID 32380704, 2020). "Specifically, our studies show that IL-1β overexpression early in amyloid pathogenesis induces a change in the microglial gene expression profile and an expansion of microglial cells that facilitates Aβ removal." (PMID 31822279, 2019). "This was associated with a reduced CXCL1, IL-1β, TNF-α-level and microgliosis, which correlated with amyloid deposition and total Aβ." (PMID 30872722, 2019). "Growing evidence from our studies and those of others suggest that interleukin 1β (IL-1β) signaling is an important mediator of amyloid-induced β-cell death in cultured and transplanted islets." (PMID 29474443, 2018). "Reduced amyloidosis in bigenic mice was concomitant with decreased glial reactivity and interleukin-1β (IL-1β) levels, and the preservation of long-term potentiation (LTP) and spatial learning, without changes in the activity of α-, β- and γ-secretases." (PMID 26202697, 2016). "The production of the precursor to SAA is the main step in the pathogenesis of amyloidosis, which is produced by inflammatory signals, IL-1β, tumor necrosis factor (TNF)-α, and IL-6." (PMID 27590627, 2016). "Over-expression of IL-1β in mouse models of amyloidosis significantly reduced Aβ plaque pathology." (PMID 41191631, 2025). "However, in human AD brain there is an approximately 10-fold increase in IL-1β(p17) compared to control samples greater again than either tauopathy or amyloidosis alone in mouse brain." (PMID 41191631, 2025). "Prior work suggests that the cytokine interleukin-1β (IL-1β) may be a key regulator of tau pathology in the presence of amyloidosis." (PMID 41191631, 2025). "Given that the tauopathy in this model appears to be dependent upon amyloidosis, IL-1β may play a greater role in the stimulation of tauopathy by amyloid than in the development of tauopathy in the absence of amyloid." (PMID 41191631, 2025).
amyloid (continued). "Upregulation in the protein levels of IL-1β (in the FC and BG of morphine-dependent macaques) was also observed in the present study, thus indicating a positive correlation between morphine-induced amyloidosis and neuroinflammation." (PMID 34527417, 2021). "We observed that FAP 0 patients already exhibited a significant increase in levels of IL-33, IL-1β and IL-10, suggesting that the alterations in immune response might occur before amyloid deposition and symptom appearance." (PMID 31253122, 2019). "Thus, it appears that IL-1β plays a role in mediating amyloid-induced β-cell death as well as amyloid-induced inhibition of β-cell proliferation." (PMID 29474443, 2018). "One possible explanation is that the anti-inflammatory microglial activity may be counteracted by enhanced astrocyte reactivity and elevated IL-1β secretion, known to promote amyloidosis in APPSWE/PS1ΔE9 mice." (PMID 27400725, 2016). "New data implicate IL-1β in facilitating the development of tauopathy while reducing amyloidosis." (PMID 25231386, 2014). "Meanwhile, colchicine therapy could be continued during anti-IL-1β administration to prevent amyloidosis even in colchicine-resistant patients." (PMID 23970817, 2013). "Likewise, beneficial regulation of inflammation by subcutaneous injection of Vitamin D3, specifically, up-regulation of IL-10 and down-regulation of IL-1β, was reported in aged F344 rats, devoid of amyloid pathology." (PMID 24204618, 2013). "However, in contrast to the negative data presented with respect to IL-1β, there is more recent data showing that IL-1β overexpression in the hippocampus of transgenic mice results in amelioration of amyloid pathology." (PMID 22454637, 2012). "Therefore, it may be the case that amyloid pathology elicits a greater increase in IL-1β than tauopathy alone and a large increase in IL-1β may be necessary to increase tauopathy." (PMID 41191631, 2025). "To assess whether the increased amyloid plaque burden resulted in an exacerbation of pro-inflammatory responses, we measured levels of the inflammation-associated molecules CXCL1, CCL3, IL-33, TNFα, IL-6, and IL-1β by multiplexed MSD ELISA." (PMID 32943069, 2020). "Because our studies showed that IL-1β induced microglial proliferation and increased Csf2ra expression in MX04+ microglia, further investigation into the role of Csf2ra in IL-1β-mediated amyloid plaque clearance is warranted." (PMID 31822279, 2019). "In amyloid-burdened brain areas detrimental pro-inflammatory cytokines such as TNF-α, IFN-γ and IL-1β are likely to be the culprit." (PMID 31120951, 2019). "IL-1β increases IL-4 production, a potent modulator of CD4 T cell responses, and administration of IL-4 in AD mice induces amyloid plaque clearance." (PMID 31822279, 2019). "Taken together, there is a possibility that the treatment with PCO causes elevation of HDL-C and enhancement of HDL functionality to induce the reduction of oxidized species (4-HNE and iNOS), inflammatory cytokines (IL-1β, IL-6, and TNF-α), and amyloid plaque size." (PMID 34439569, 2021). "Interestingly, islet amyloid mediated decrease in phospho-PKB levels in β-cells correlated with elevated islet IL-1β levels in cultured human islets." (PMID 29474443, 2018). "Thus, the relationship between NLRP3 inflammasome activation and enhanced amyloidosis and tauopathy need not passage through IL-1β." (PMID 41191631, 2025). "Furthermore, the favourable outcome of the young transplanted patient with anti-IL-1β therapy points to efficacy in preventing rather than reversing manifest amyloidosis." (PMID 39025961, 2024).
amyloid (continued). "Progress of CKD despite clinical and serological efficacy of anti-IL-1β therapy, in principle, leaves two explanatory options: First, amyloidosis might be at least in part due to a mechanism independent of IL-1 in the first place." (PMID 39025961, 2024). "NLRP3 selective inhibitors (e.g. MCC950, OLT1177) that have shown effective for reversing AD pathology in amyloid mouse models, might not be enough to suppress IL-1β levels and the detrimental effects of IL-1β in human AD." (PMID 38539253, 2024). "However, disrupting CCR2 signaling and recruitment of BMD-mononuclear phagocytes did not alter the ability of IL-1β to reduce amyloid plaque burden." (PMID 31822279, 2019). "Our interpretation is that amyloid-driven IL-1β/TNF-α expression is not functional in tgHpaSwe." (PMID 30872722, 2019). "Postmortem studies indicated increased levels of MCP-1 and Interleukin-1β (IL-1β) in parietal cortex and a trend toward increased levels of IL-1β and MCP-1 in frontal cortex in older adults with amyloid beta deposition compared to age-matched individuals without amyloid." (PMID 37686198, 2023). "We have previously shown that sustained expression of IL-1β in the hippocampus of APP/PS1 mice decreases amyloid plaque burden independent of recruited CCR2+ myeloid cells, suggesting resident microglia as the main phagocytic effectors of IL-1β-induced plaque clearance." (PMID 31822279, 2019).
neuropathic pain (45 papers, 2013 to 2025). Chronic pain caused by damage to nerve fibers. "MMP-9 induces early-phase neuropathic pain by activating interleukin (IL)-1β and microglia in the early phase, while MMP-2 is implicated in the development of late-phase neuropathic pain." (PMID 39654618, 2024). "Repeated EA interventions have a time-dependent cumulative analgesic effect in neuropathic pain rats, which is closely associated with its regulatory effects on NK cells, splenic IL-2, β-EP, and plasma IL-2, IL-1β, IFN-γ and TGF-β levels." (PMID 25158599, 2014). "Furthermore, the findings suggested that IL-1β and IL-6 are responsible for the emotional dysfunction associated with neuropathic pain." (PMID 33432004, 2021). "Considering that IL-1β facilitates excitatory synaptic transmission in the spinal dorsal horn, the in vivo effect of cilnidipine in this model of neuropathic pain may be linked to its inhibitory action on microglial P2X7Rs and IL-1β release." (PMID 33670748, 2021). "Notably, autophagy is a key activator of inflammatory responses, and a loss of function in BECLIN-1 has been found to dysregulate immune responses, including microglia release of IL1-β, a cytokine which has consistently been implicated in mouse neuropathic pain models." (PMID 39809538, 2025). "EE can relieve neuropathic pain by reducing inflammatory mediators, such as proinflammatory cytokines (IL-1β, TNF-α, IL-6) and chemokines (CCL2, CCL3), among others, increasing anti-inflammatory substances (IL-10, Arg-1, CX3CL1) in the periphery and CNS." (PMID 40190342, 2025). "In our study, PTP1B‐IN‐1 administration effectively suppressed the elevated Iba‐1, GFAP, TNF‐α, IL‐6, and IL‐1β in SNI‐induced neuropathic pain rats." (PMID 38334011, 2024). "Studies have shown that the expression levels of NLRP3 and IL-1β are elevated in several rodent neuropathic pain models." (PMID 36361825, 2022). "Several pro-inflammatory cytokines, including IL-1β, IL-6, IL-18, and TNF-α, have been implicated in the development of neuropathic pain." (PMID 35770074, 2022). "During pathogenesis of neuropathic pain, activated microglia produce and release a variety of pro-inflammatory cytokines (e.g., IL-1β, TNFα, IL-6, and CCL2) and BDNF to sensitize spinal neurons." (PMID 33739978, 2021). "Studies on the peripheral mechanism of neuropathic pain indicated that IL-1β induce peripheral sensitization of sensory neurons and mechanical hyperalgesia." (PMID 30971286, 2019). "Studies report the involvement of proinflammatory cytokines in pathological processes of pain, including TNF-α and IL-1β, which are found at high levels in animal models of neuropathic pain." (PMID 31049124, 2019). "It has also been reported that ghrelin attenuates pain behaviors by decreasing TNF-α and IL-1β levels in the spinal cord and in a sciatic nerve injury model of neuropathic pain." (PMID 28182729, 2017). "Pro-inflammatory cytokines such as IL-1β, IL-6, and TNF-α have been associated with the behaviors of hyperalgesia and mechanical allodynia in the CCI model of neuropathic pain." (PMID 24605047, 2014). "Several studies have shown that the mRNA and protein levels of the pro-inflammatory cytokines TNF-α, IL-1β and IL-6 increased following chronic morphine injection and neuropathic pain." (PMID 24573601, 2014). "In vivo, EGCG can inhibit the expressions of TLR4, NF-κB, HMGB1, TNF-α, and IL-1β, and promote the expression of IL-10 in neuropathic pain rats." (PMID 24692852, 2014). "Recent studies have strongly supported that spinal cord glia (including astrocytes and microglia) and proinflammatory cytokines, such as IL-1β, are involved in the induction and maintenance of neuropathic pain." (PMID 23585846, 2013).
neuropathic pain (continued). "In experimental neuropathic pain models, repeated stimulation has been shown to downregulate pro-inflammatory cytokines (e.g., spinal IL-1β, hippocampal TNF-α), upregulate IL-10, and suppress microglial and astrocytic activation, thereby fostering adaptive plasticity and reducing hypersensitivity." (PMID 41245860, 2025). "MMP-9 induces the early development of neuropathic pain by mediating the early cleavage of IL-1β and activation of microglia, while MMP-2 is engaged in the sustainment of neuropathic pain in late stages through modulating the cleavage of IL-1β and activation of astrocytes." (PMID 36204142, 2022). "Our findings suggest that neuropathic pain changes glycinergic activity, which may affect the signal output from CeA; meanwhile, IL-1β modulates the integrated summation and output to and from CeA, and thus the emotional perception of neuropathic pain." (PMID 35806360, 2022). "Since not only IL-1β, but also endogenous IL-1α and IL-1ra are able to bind to IL-1 receptors, these results suggest that the effect of exogenous IL-1ra on both astrocyte activity and P450c17 expression is mediated in large part by blockade of IL-1β’s action in this neuropathic pain model." (PMID 31281242, 2019). "Taken together, the present study suggests that coadministration of tramadol and propentofylline could exert synergistic antiallodynic effects on SNL-induced neuropathic pain by inhibiting SNL-induced IL-1β related pathways." (PMID 24009718, 2013). "Similarly, IL-1β and IL-6 are related to the pathogenesis of neuropathic pain." (PMID 37081929, 2023). "We further found that CKO of neuronal FcγRI in the DRG or Syk inhibition can attenuate CCI‐induced Syk activation and NF‐κB p65 activation in DRG neurons and decrease NLRP3, IL‐1β, and IL‐18 expression levels in DRG after neuropathic pain." (PMID 36727833, 2023). "In the case of hesperidin, its antihyperalgesic effects in neuropathic pain have been related to the presence of cytokines concentrations (TNF-α, IL-1β and IL-6) in both peripheral and central tissues." (PMID 34371971, 2021). "It is known that IL-1β, IFN-γ, IL-17, IL-6 and TNFα are increased in nervous tissue in animal models of neuropathic pain, but also in cerebrospinal fluid and blood of patients with neuropathic pain." (PMID 32708184, 2020). "Studies have shown that NF-κB is observed to regulate the expression of pro-inflammatory cytokines such as TNF-α, IL-1β and IL-6 in DRG and spinal cord in neuropathic pain." (PMID 33095154, 2020). "Minocycline has also indicated to reduce the cytokine levels (IL-1β, TNF-α, and IL-6), which promoted neuro-inflammation and decreased pain behavior in a CCI model of neuropathic pain." (PMID 27221523, 2016). "For example, spinal LXA4 and its aspirin-triggered form reduced TNF, IL-1β and IL-6 mRNA and protein levels in the DRG in a neuropathic pain model and in the spinal cord in a model of bone cancer-induced pain." (PMID 24086560, 2013). "Interestingly, it has been determined that the upregulation of IL-6, IL-1β, and TNF-α, among others, strongly influences neuropathic pain." (PMID 39684195, 2024). "Consistently, in the present study, the intrathecal injections of NALP1 siRNA not only significantly down-regulated IL-1β maturation but also attenuated neuropathic pain, which further suggests that the activated spinal NALP1 inflammasome contributes to SNI-induced neuropathic pain." (PMID 27381056, 2016). "Thus, an immunotherapy that modulates the infiltration of immune cells, such as macrophages, and the upregulation of pro-inflammatory cytokines (e.g., IL-1β and TNF-α) would be a useful preventive treatment for neuropathic pain." (PMID 26797636, 2016).